GMFG (glia maturation factor gamma)
Diseases named in the same sentence as GMFG in open-access papers (continued):
Sharing a sentence is not in itself a finding about the gene and the disease.
glioma (3 papers, 2021 to 2024). A benign or malignant brain and spinal cord tumor that arises from glial cells (astrocytes, oligodendrocytes, ependymal cells). "High GMFG expression significantly correlated with the malignancy of gliomas and was strongly associated with IDH1/2 wild-type, 1p19q codeletion, and ME subtypes." (PMID 35845613, 2022). "To further validate our findings, we performed IHC staining for one of the TAMs markers (CD163) and found that GMFG expression was significantly associated with CD163 expression in gliomas." (PMID 35845613, 2022). "Importantly, this study showed that GMFG is significantly associated with the infiltration of macrophages in the tumor microenvironment of gliomas." (PMID 35845613, 2022). "In this study, public datasets comprising 2,518 gliomas samples were used to explore GMFG expression and its correlation with malignancy in gliomas." (PMID 35845613, 2022). "Our analyses regarding GMFG expression and cell markers were consistent with GMFG association with the remodeling of the tumor microenvironment and TAM infiltration in gliomas." (PMID 35845613, 2022). "In this study, we demonstrate that GMFG can be a complementary marker when combined with the methylated status of MGMT promoter for predicting TMZ response in gliomas." (PMID 35845613, 2022). "To further validate the correlation between GMFG and immune infiltration in gliomas, we analyzed single-cell sequencing datasets of the gliomas from the TISCH database." (PMID 35845613, 2022). "Results showed that GMFG expression was higher in gliomas compared with normal brain tissues in the four datasets." (PMID 35845613, 2022). "The Kaplan–Meier analysis was performed to determine the prognostic role of GMFG and its association with temozolomide (TMZ) response in gliomas." (PMID 35845613, 2022). "The results showed that high GMFG expression in gliomas predicted a worse prognosis compared with low GMFG expression in TCGA, CGGA, Rembrandt, and Gravendeel datasets." (PMID 35845613, 2022). "Bioinformatic prediction and IHC analysis revealed that GMFG expression obviously correlated with the macrophage marker CD163 in gliomas." (PMID 35845613, 2022). "Our findings were consistent with our previous study, which provided more reliable confirmation of the role of GMFG in glioma." (PMID 35845613, 2022). "In this study, we found that the GMFG was significantly upregulated in gliomas and its expression increased with glioma grade." (PMID 35845613, 2022). "In this study, we explored the expression of GMFG in gliomas and its relationship with gliomas malignancy using public datasets and an in-house cohort." (PMID 35845613, 2022). "Immunohistochemistry (IHC) staining was performed to determine the expression of GMFG in gliomas using an in-house cohort that contained 120 gliomas samples." (PMID 35845613, 2022). "In the TCGA dataset, we found that GMFG expression was significantly higher in gliomas with unmethylated MGMT promoter than in those with methylated MGMT promoter." (PMID 35845613, 2022). "We found that the expression of GMFG in gliomas was significantly increased and correlated with tumor malignancy." (PMID 35845613, 2022). "Analysis of GMFG expression in the Oncomine dataset revealed a significant increase in GMFG expression in brain and CNS cancer tissues." (PMID 35845613, 2022). "Herein, the expression of GMFG was positively correlated with TAMs in gliomas." (PMID 35845613, 2022). "Importantly, in the four public datasets, high GMFG expression predicted a worse prognosis of gliomas, indicating that GMFG can be a novel prognostic biomarker for patients with LGG and GBM." (PMID 35845613, 2022). "Importantly, this study demonstrates that GMFG is a crucial marker for TMZ response in gliomas." (PMID 35845613, 2022). "Moreover, GMFG expression significantly correlated with macrophage infiltration and might play a role in influencing the gliomas microenvironment." (PMID 35845613, 2022).
glioma (continued). "In addition, GMFG was significantly enriched in IDH wt gliomas, especially in GBM." (PMID 35845613, 2022). "In addition, the results of TISCH indicated that the main immune cells producing GMFG mRNA in glioma might be CD8 T cells and macrophages." (PMID 35845613, 2022). "Results of GEPIA showed that GMFG was significantly elevated in GBM and lower grade gliomas (LGG, WHO grades I–III) compared with normal brain tissues." (PMID 35845613, 2022). "In contrast, it demonstrates a negative correlation with GMFG, S100A6, and S100A11, all of which are associated with promoting glioma progression." (PMID 38674418, 2024). "The GMFG expression was higher in gliomas compared with non-tumor brain tissues both in public datasets and in-house cohort." (PMID 35845613, 2022). "The IHC data also indicated that GMFG expression was significantly higher in glioma tissues compared with non-tumor tissues." (PMID 35845613, 2022). "Therefore, we speculate that GMFG regulates the infiltration of M2 macrophages, which in turn promotes TMZ resistance in glioma cells." (PMID 35845613, 2022). "Previously, the GMFG protein was not considered to participate in the development of gliomas." (PMID 35845613, 2022).
acute myeloid leukemia (2 papers, 2021 to 2022). Acute myeloid leukemia (AML) is a group of neoplasms arising from precursor cells committed to the myeloid cell-line differentiation. "One study found that GMFG was markedly elevated in GBM, LGG, kidney clear carcinoma (KIRC), and acute myeloid leukemia (LAML) cancers." (PMID 35845613, 2022). "Among 33 different cancers samples, GMFG expressions in lymphoid neoplasm diffuse large B-cell lymphoma (DLBC), acute myeloid leukemia (LAML) and thymoma (THYM) were obviously higher than that in other cancer types." (PMID 33863293, 2021).
bladder cancer (2 papers, 2021 to 2025). "High expression of GMFG was correlated with early pathological stage in bladder cancer (BLCA) (P = 0.016), LUAD (P = 0.015), skin cutaneous melanoma (SKCM) (P = 0.006) and thyroid cancer (THCA) (P = 0.01), but was linked with advanced pathological stage in stomach cancer (STAD) (P = 0.028)." (PMID 33863293, 2021).
chordoma (2 papers, 2024 to 2025). Chordomas are rare malignant tumors arising from embryonic remnants of the notochord in axial skeleton. "Hypoxic microenvironment reprogramed CAFs into ERS-CAF subtype, which can regulates SPP1macrophage to aggravate chordoma progression via the IER2/GMFG/ITGB1 axis in chordoma." (PMID 41425545, 2025). "To clarify the regulatory role of the GMFG/ITGB1 signaling axis in chordoma progression, we introduced exogenous GMFG to the CAF medium." (PMID 39207055, 2024). "To unveil GMFG's downstream targets in regulating chordoma progression, we used RNA‐seq to investigate the mRNA expression profiles of chordoma cells before and after incubation with exogenous GMFG." (PMID 39207055, 2024). "To delve into the biological behavior regulated by the GMFG/ITGB1 axis that affected the progression of chordoma, we first reanalyzed the bulk RNA‐seq data (n = 126)." (PMID 39207055, 2024). "Additionally, we conducted correlation analysis between ITGB1 and GMFG using two chordoma bulk RNA‐seq datasets (GSE239531 and GSE205457) from the GEO database as well as RNA‐seq data involving 42 bone tumor cell lines from the CCLE database." (PMID 39207055, 2024). "Collectively, the findings suggest that ERS‐CAF regulates SPP1+ macrophage to aggravate chordoma progression via the IER2/GMFG/ITGB1 axis, which may be targeted therapeutically in future." (PMID 39207055, 2024). "IER2 stimulated GMFG factor secretion by ERS‐CAF, which then promoted chordoma malignant progression through binding with ITGB1 on tumor cells." (PMID 39207055, 2024). "To further understand the functional role of GMFG in chordoma progression, we then employed bulk RNA‐seq and DSP techniques to identify GMFG‐mediated downstream signaling pathways." (PMID 39207055, 2024). "The hypoxic chordoma microenvironment induces upregulation of IER2 in CAF to stimulate its ERS effect and then release GMFG cytokine." (PMID 39207055, 2024). "The paracrine GMFG signaling from ERS‐CAF promoted tumor cell proliferation, migration, and invasion via binding with ITGB1 on tumor cell, thereby driving chordoma progression." (PMID 39207055, 2024). "Moreover, we identified a significant positive correlation between GMFG and ITGB1 expression based on the bulk RNA‐seq data from 126 chordoma samples." (PMID 39207055, 2024). "The current study demonstrated that the hypoxic chordoma microenvironment could induce sustained expression of IER2 in CAF to stimulate its ERS effect and then released GMFG cytokine." (PMID 39207055, 2024). "The exact mechanisms of how the GMFG/ITGB1 signaling influences chordoma biology is not known." (PMID 39207055, 2024).
iron deficiency (2 papers, 2019 to 2022). "Knock-down of GMFG in macrophages exhibited an iron deficiency response and enhanced expression of M2 macrophage markers toward the M2 phenotype." (PMID 35845613, 2022).
liver cancer (2 papers, 2021 to 2023). An epithelial or non-epithelial malignant neoplasm that arises from the liver. "In contrast, GMFG was negatively correlated with most of the immunomodulators in THYM, and only a week correlation was observed between GMFG and immunomodulators in DLBC, LAML, and liver cancer (LIHC)." (PMID 33863293, 2021).
pancreatic cancer (2 papers, 2021 to 2026). "GMFG is transported into pancreatic cancer cells where it binds to intracellular tensin-4 (TNS4), promoting FAK/AKT phosphorylation and coordinating two programs critical for metastatic outgrowth: enhanced cell-ECM adhesion and increased de novo fatty acid synthesis." (PMID 42314060, 2026).
Sepsis (2 papers, 2023 to 2024). Sepsis is defined as life-threatening organ dysfunction caused by a dysregulated host response to infection. "A comprehensive analysis was conducted to investigate the impact of senescence-related genes on sepsis, and 8 hub genes (IGFBP7, GMFG, IL10, IL18, ETS2, HGF, CD55, MMP9) associated with senescence were identified." (PMID 38259686, 2023). "In this study, we identified 8 senescence-related genes (IGFBP7, GMFG, IL10, IL18, ETS2, HGF, CD55, and MMP9) and developed a diagnostic model for the prediction of sepsis occurrence." (PMID 38259686, 2023). "Consensus cluster analysis we successfully classified sepsis patients into two distinct groups based on the expression of 8 hub genes (IGFBP7, GMFG, IL10, IL18, ETS2, HGF, CD55, and MMP9)." (PMID 38259686, 2023).
thyroid cancer (2 papers, 2021 to 2023). "Low GMFG expression was observed in 13 tumors: adrenocortical carcinoma (ACC), BLCA, BRCA, COAD, ESCA, KICH, LUAD, LUSC, prostate adenocarcinoma (PRAD), READ, thyroid carcinoma (THCA), uterine carcinosarcoma (UCS), and UCEC." (PMID 37372337, 2023).
atherosclerosis (1 paper, 2025). A disease characterized by the build-up of fatty material and calcium deposition in the arterial wall resulting in partial or complete occlusion of the arterial lumen. "Machine learning-based techniques, including LASSO, Boruta, Support Vector Machine, and Random Forest, were employed to specifically identify CTSC, TGFBI, and GMFG as potential diagnostic biomarkers associated with SMC activity in atherosclerosis." (PMID 40299531, 2025). "Through single-cell RNA sequencing and machine learning, we pinpointed CTSC, TGFBI, and GMFG as key biomarkers for atherosclerosis risk stratification." (PMID 40299531, 2025). "In conclusion, a Venn diagram illustrated TGFBI, GMFG, and CTSC as key genes associated with both atherosclerosis and disulfidptosis." (PMID 40299531, 2025). "In the smooth muscle cell (SMC)-focused in vitro model of atherosclerosis, RT-qPCR analysis demonstrated that the expression levels of CTSC, TGFBI, and GMFG were significantly elevated compared to those in the control group." (PMID 40299531, 2025).
bile duct cancer (1 paper, 2021). "In contrast, high expression of GMFG was associated with better OS in SKCM (HR = 0.59, P < 0.001) and THYM (HR = 0.098, P = 0.031), as well as better DFS in bile duct cancer (CHOL) (HR = 0.2, P = 0.003)." (PMID 33863293, 2021). "In contrast, high expression of GMFG was associated with better OS in skin cutaneous melanoma (SKCM) (HR = 0.59, P < 0.001) and thymoma (THYM) (HR = 0.098, P = 0.031), as well as better DFS in bile duct cancer (CHOL) (HR = 0.2, P = 0.003)." (PMID 33863293, 2021).
Infertility (1 paper, 2025). "The candidate gene GMFG may be involved in the regulation of bacterial infections that lead to infertility in cattle." (PMID 39794685, 2025).
ocular melanoma (1 paper, 2021). A melanoma that arises from the structures of the eye or ocular adnexa. "High expression of GMFG predicted worse OS in GBM (HR = 1.5, P = 0.017), LGG (HR = 2.2, P < 0.001), LUSC (HR = 1.4, P = 0.022) and ocular melanomas (UVM) (HR = 7, P < 0.001), as well as worse DFS in LGG (HR = 1.8, P < 0.001) and prostate cancer (PRAD) (HR = 1.9, P = 0.004)." (PMID 33863293, 2021).
prostate carcinoma (1 paper, 2021). A carcinoma that arises from epithelial cells of the prostate gland. "For survival outcome, high expression of GMFG predicted worse OS in GBM (HR = 1.5, P = 0.017), LGG (HR = 2.2, P < 0.001), LUSC (HR = 1.4, P = 0.022) and UVM (HR = 7, P < 0.001), as well as worse DFS in LGG (HR = 1.8, P < 0.001) and prostate cancer (PRAD) (HR = 1.9, P = 0.004)." (PMID 33863293, 2021).
rectal cancer (1 paper, 2021). A primary or metastatic malignant neoplasm that affects the rectum. "GMFG was positively correlated with immunomodulators genes in most cancer, and the most positive correlations between GMFG and these genes were found in TGCT, SKCM, UVM, LUSC and colon and rectal cancer (COADREAD)." (PMID 33863293, 2021).
tumor (13 papers, 2021 to 2025). "Increased GMFG expression is associated with tumor-associated macrophages (TAMs) infiltration and with a bad response to TMZ treatment." (PMID 35845613, 2022). "Bioinformatic analysis of GMFG in pan-cancers revealed that GMFG causes different survivals for different cancers through modulating tumor progression, immune response status, and tissue-specific tumor microenvironment." (PMID 35103856, 2022). "CIBERSORT analysis for the proportion of tumor-infiltrating immune cells (TIICs) suggested that expression of GMFG was positively association with multiple kinds T-cell in BC." (PMID 34367945, 2021). "Our study preliminarily identified that GMFG may cause different survivals for different cancers through modulating tumor progression, immune response status and tissue-specific tumor microenvironment (TME)." (PMID 33863293, 2021). "Glia maturation factor-γ (GMFG) is a protein that regulates tumor progression, immune response modulation, and the tissue-specific tumor microenvironment." (PMID 40756570, 2025). "Our analyses indicated that GMFG exerted its biological function through interaction with ITGB1 on tumor cells." (PMID 39207055, 2024). "To further determine the biological function of GMFG, we silenced GMFG in CAF while introducing exogenous GMFG to CAF culture media to observe their impact on tumor biology." (PMID 39207055, 2024). "Our results showed that exogenous GMFG factor significantly enhanced the proliferation, migration, and invasion ability of U‐CH1 and UM‐Chor1 cells, while GMFG silence on CAF mitigated tumor cell malignancy." (PMID 39207055, 2024). "In vivo subcutaneous tumorigenesis experiments also unveiled that local injection of exogenous GMFG significantly promoted tumor growth and proliferation." (PMID 39207055, 2024). "We used TCGA to analyze the expression of GMFG in tumor and normal control samples in various tissue types." (PMID 37372337, 2023). "Although we found that GMFG plays a role in TNBC progression, the underlying mechanism of GMFG’s promotion of tumor metastasis still needs to be further explored." (PMID 37372337, 2023). "In the present study, we found that lncRNA LANCL1-AS1 acted as a tumor suppressor in NSCLC by regulating the miR-3680-3p/GMFG axis." (PMID 36941990, 2023). "Most importantly, however, GMFG has also been reported to be closely correlated to the tumor’s prognosis." (PMID 37372337, 2023). "More importantly, the tumor-promoting role of GMFG knockout was also validated in mice bearing A549 xenografts." (PMID 35383531, 2022). "The tumor-promoting or tumor-suppressing functions of Glia maturation factor gamma (GMFG) were described in several cancers." (PMID 35383531, 2022). "Mounting evidence has demonstrated that GMFG is beneficial or detrimental in the cancer progression by regulating tumor cell behaviors." (PMID 35383531, 2022). "Migration and invasion of cancer cells are necessary for tumor metastasis, and, in this regard, GMFG may enhance tip cell sprouting, tube formation, and the directional migration of monocytes, neutrophils, and T-lymphocytes." (PMID 37372337, 2023). "Considering the main function of GMFG in actin remodeling, which is vital for immune response, angiogenesis, cell division and motility, GMFG is supposed to have important roles in tumor development, while up to now, only two studies described the role of GMFG in cancers." (PMID 33863293, 2021). "Overall, our findings may help to understand the real mechanisms of GMFG in regulating the tumor progression, immune response status and tissue-specific TME of different cancers." (PMID 33863293, 2021). "Thus, our research data suggest that GMFG plays an important role in tumor development largely through the protein-protein interaction." (PMID 33863293, 2021).